CREB3L4 (cAMP responsive element binding protein 3 like 4)
Diseases named in the same sentence as CREB3L4 in open-access papers:
CREB3L4 is named in the same sentence as 50 diseases in open-access papers, as found by Europe PMC text mining. Sharing a sentence is not in itself a finding about the gene and the disease. The quoted sentences say what the papers report.
prostate carcinoma (20 papers, 2009 to 2025). A carcinoma that arises from epithelial cells of the prostate gland. "Creb3L4, by contrast, is linked to chromatin organization during spermiogenesis and prostate cancer, but recently, it has been linked to adipocyte function." (PMID 31293620, 2019). "We also showed that CREB3L4 directly associates with AR, to enhance AR-induced transactivation of its downstream genes, in prostate cancer cells." (PMID 28338058, 2017). "CREB3L4 is known to primarily be expressed in the prostate and some breast cancer cell lines and has been linked to diverse roles involving chromatin organization in spermiogenesis, adipocyte regulation, and dysregulation in prostate cancer." (PMID 34367349, 2021). "In prostate cancer, CREB3L4 plays a critical role in promoting cell proliferation and is functionally linked to AR-regulated oncogenic pathways." (PMID 41155247, 2025). "Emerging evidence suggests that CREB3L4 contributes to prostate cancer progression not only by enhancing cell proliferation, but also by influencing differentiation and survival pathways." (PMID 41155247, 2025). "In prostate cancer, CREB3L4 is considered to facilitate the prostatic cancer cell proliferation via interacting with the androgen receptor." (PMID 38303702, 2024). "Aberrant CREB3L4 expression is associated with the pathogenesis of HCC, prostate cancer and gastric cancer, but its targets in the pathogenesis of these cancers are still not well defined." (PMID 38303702, 2024). "Previous study showed that CREB3L4 promoted the migration and invasion of gastric cancer and prostate cancer." (PMID 38303702, 2024). "One of these groups was originally interested in identifying androgen-regulated genes in human prostate cancer cells, and so CREB3L4 cDNA was isolated from LNCaP human prostate cancer cells treated with the synthetic androgen R1881." (PMID 31334233, 2019). "CREB3L4 is predominantly expressed in prostatic tissue and in breast cancer and prostate cancer cell lines." (PMID 31334233, 2019). "In summary, our findings demonstrate that CREB3L4 plays a key role in prostate cancer cell proliferation, justifying its further study as a possible prostate cancer biomarker and therapeutic target." (PMID 28338058, 2017). "CREB3L4 is upregulated in both a prostate cancer cell line (LNCaP) and in primary prostate cancer cells." (PMID 28056099, 2017). "To examine the relationship between CREB3L4 and AR, with regard to prostate cancer cell proliferation, we performed reporter assays using a PSA gene promoter construct." (PMID 28338058, 2017). "We first questioned the molecular mechanism of how CREB3L4 gene expression is regulated in prostate cancer cells." (PMID 28338058, 2017). "Our overall results demonstrate a role for CREB3L4 in modulating AR action, suggesting an interrelationship, and an AR-ER stress-CREB3L4 signaling axis, in prostate cancer cell proliferation." (PMID 28338058, 2017). "Collectively, we demonstrated that CREB3L4 is required for proliferation of prostate cancer cells, and that CREB3L4 is a crucial activator of AR function." (PMID 28338058, 2017). "In this study, we found that CREB3L4 is essential for prostate cancer cell proliferation, through its modulation of AR activity, which reciprocally, is upstream of CREB3L4 expression (perhaps suggesting some type of positive feedback)." (PMID 28338058, 2017). "Since AR plays a crucial role in prostate cancer cell proliferation, and is a common therapeutic target, we assessed possible roles for CREB3L4 in the AR signal cascade." (PMID 28338058, 2017). "From this background, we used LNCaP cells as an experimental model for studying androgen-dependent regulation of CREB3L4, with specific regard to prostate cancer cell proliferation." (PMID 28338058, 2017). "To this end, we explored a role for CREB3L4 in the androgen-dependent prostate cancer cell line, LNCaP." (PMID 28338058, 2017).
prostate carcinoma (continued). "CREB3L4 was originally identified as a highly expressed and androgen-induced protein in prostate cancer cells." (PMID 21711675, 2011). "These include the endoplasmic reticulum (ER) originating transcription factors CREB3L4 and CREBL1 (also known as ATF6B), which we find are associated with an 14% and 21% increased risk of prostate cancer overall, respectively, and that are expressed in the prostate epithelium." (PMID 38878676, 2024). "Besides, high CREB3L4 is overexpressed in prostate cancer and gastric cancer patients with a poor overall survival." (PMID 38303702, 2024). "Aberrant CREB3L4 expression had been observed in prostate cancer and gastric cancer." (PMID 38303702, 2024). "Interestingly, CREB3L4, known for its role in proliferating prostate cancer cells, was significantly down-regulated in all kidney cancer nodules (x(PTA) = −1.40, x(PTB) = −1.74, x(CWM) = −1.95)." (PMID 38132440, 2023). "To test this hypothesis, we selected CREB3L4, which has been described to be expressed in several prostate-cancer-derived cell lines, including PC-3 cells." (PMID 36611993, 2023). "For CREB3L4, which is expressed in BRCA and HNSC, the cancer associated with it is prostate cancer." (PMID 36016607, 2022). "The “prostate cancer” pathway also comprises genes that are relatively specific to the (human) prostate (CREB3L4, KLK2, NKX3-1 and SRD5A2), proto-oncogenes (EGFR, NRAS, PDGFRA and PDGFRB), and druggable candidates (CDKN1A, CTNNB1, EGFR, NRAS, PDGFRA, PDGFRB, PIK3CD and PIK3CG)." (PMID 34768937, 2021). "Creb3L4 is shown to inhibit Creb3L1 activity in prostate cancer cells." (PMID 31293620, 2019). "Thus, we posit that CREB3L4 is an essential mediator of AR-IRE1α-induced prostate cancer progression." (PMID 28338058, 2017). "To test this hypothesis, we examined the relationship between IRE1α pathway signaling and CREB3L4 in AR-induced prostate cancer cell proliferation." (PMID 28338058, 2017). "We speculate that regulation of the AR-IRE1α-CREB3L4 pathway in the presence of androgen, may maximize the effect of androgen on proliferation of prostate cancer cells." (PMID 28338058, 2017). "Finally, the higher abundance of CREB3L4 in prostate cancer cells and its inducibility by androgens are in line with a crucial role for CREB3L4 in prostate carcinogenesis." (PMID 21711675, 2011). "Thus, we speculated whether CREB3L4 may also play a critical role in regulating prostate cancer cell proliferation, through interacting with AR." (PMID 28338058, 2017). "However, the biological role of CREB3L4 in prostate cancer cell proliferation previously remained unknown." (PMID 28338058, 2017). "Additionally, we demonstrated that androgen-induced CREB3L4 expression is in part regulated by AR directly, and in part indirectly, by IRE1α signaling, suggesting that a distinct AR-ER stress-CREB3L4 regulatory axis also plays a role in prostate cancer proliferation." (PMID 28338058, 2017). "KEGG pathway enrichment analysis revealed that the significantly enriched pathways were PI3K-Akt signaling, prostate cancer, cell cycle, Wnt signaling, and pathways in cancer; this analysis also showed that CCNE2, MYC, and CREB3L4 were the key involved genes." (PMID 28056099, 2017). "Altogether, these results showed that CREB3L4 could work as the collaborative partner of HOXB13, potentially through direct protein–protein interactions, to promote its proliferative activity in prostate-cancer-derived PC-3 cells." (PMID 36611993, 2023). "Finally, the “prostate cancer” pathway also includes DEGsSD that are relatively specific to the (human) prostate (SRD5A2, KLK2, NKX3-1 and CREB3L4), proto-oncogenes (EGFR, PDGFRA, PDGFRB, NRAS) and druggable candidates (PIK3CD, CTNNB1, PIK3CG, CDKN1A)." (PMID 34768937, 2021).
breast carcinoma (7 papers, 2016 to 2025). "CREB3L4 encodes the cyclic AMP-responsive element-binding protein 3-like protein 4, a transcription factor responsible for breast cancer progression." (PMID 38028209, 2023). "In breast cancer, CREB3L4 has been shown to bind to the promoter region of proliferating cell nuclear antigen (PCNA), with knockdown of CREB3L4 increasing cell apoptosis and cell cycle arrest." (PMID 41301006, 2025). "Anti-HER2-targeted therapy has downregulated CREB3L4 expression in breast cancer samples." (PMID 38028209, 2023). "CREB3L4 and PRDM1 disproportionately affect the type I and II LacNAc pathway in luminal breast cancer: Our analysis suggests that CREB3L4 (enrichment p-value = 0.036) and PRDM1 (enrichment p-value = 0.039) may regulate the type 1 and 2 LacNAc pathways." (PMID 34367349, 2021).
Obesity (5 papers, 2014 to 2024). Accumulation of substantial excess body fat. "It has been revealed that Creb3l4 knockout mice exhibit glucose tolerance and decreased insulin sensitivity, suggesting a role of CREB3L4 in both obesity and type 2 diabetes." (PMID 37569434, 2023). "Because fat diet or aging is known to be associated with the development of obesity, we examined the effects of Creb3l4 gene subjected to low-fat diet (LFD) or aging process on body composition and obesity risk." (PMID 26302066, 2015). "Because Creb3l4 is expressed in other tissues, the generation and characterization of adipocytes-specific knockout mice will be required to determine the roles of CREB3L4 in obesity and related metabolic diseases." (PMID 25412305, 2014). "CREB3L4 is a potential therapeutic target for treating obesity and metabolic syndrome." (PMID 39254691, 2024).
gastric cancer (3 papers, 2020 to 2026). A primary or metastatic malignant neoplasm involving the stomach. "Up to now, only one study indicated that CREB3L4 involved in the tumor progression in gastric cancer via modulating VEGFA expression." (PMID 38303702, 2024). "Notably, knockdown of CREB3L4 inhibited autophagy and alleviated cisplatin resistance in gastric cancer cells by down-regulating BAG3." (PMID 42098970, 2026). "Furthermore, BAG3 expression was inhibited following CREB3L4 knockdown in gastric cancer cells." (PMID 42098970, 2026). "However, whether the CREB3L4/BAG3 axis regulates autophagy and contributes to cisplatin resistance in gastric cancer cells remains unclear." (PMID 42098970, 2026).
hepatocellular carcinoma (3 papers, 2017 to 2024). A malignant tumor that arises from hepatocytes. "Notably, CREB3L4 contributes to hepatocellular carcinoma development by promoting the RHEB-mTORC1 pathway and reducing sensitivity to chemotherapy drugs." (PMID 39254691, 2024). "In addition, the 1q21 amplicon containing CREB3L4 is frequently detected in hepatocellular carcinoma, and CREB3L4 is significantly overexpressed in tumor tissues compared with nontumorous tissue counterparts." (PMID 28056099, 2017). "This study was designed to explore the roles of CREB3L4 in the pathogenesis and drug resistance of hepatocellular carcinoma (HCC)." (PMID 38303702, 2024).
Insulin resistance (3 papers, 2014 to 2023). Increased resistance towards insulin, that is, diminished effectiveness of insulin in reducing blood glucose levels. "Indeed, Creb3l4-KO mice subjected to an HFD showed increased hyperplastic WAT, due to enhanced adipogenesis, which may contribute to overcome HFD-induced glucose intolerance and insulin resistance." (PMID 25412305, 2014).
diabetes (2 papers, 2015 to 2023). "Creb3l4 has a critical role in metabolic phenotypes and a better understanding of its function may provide improved insight into the etiology of diabetes and other metabolic disorders." (PMID 26302066, 2015).
glioma (2 papers, 2023 to 2024). A benign or malignant brain and spinal cord tumor that arises from glial cells (astrocytes, oligodendrocytes, ependymal cells). "Overexpression of the genes whose transcripts act as potential targets fordysregulated miRNAs in the IDHmut and IDHwt groups is observed in moreaggressive glioma types: FKBP9 – CREB3L4, MCM4, MCM6, PSMB2, ARID1A, ARL4C, GRPEL2, and C9orf64." (PMID 39539523, 2024).
Huntington disease (2 papers, 2014 to 2024). Huntington disease (HD) is a rare neurodegenerative disorder of the central nervous system characterized by unwanted choreatic movements, behavioral and psychiatric disturbances and dementia. "Although most of the genes were involved in several of these pathways, some of them were restricted to Huntington’s disease (AP2B1, CREB3L4, POLR2H and SOD1), to Alzheimer ́s disease (NAE1, FAS) or to Parkinson’s disease (PARK7)." (PMID 24742402, 2014).
depression (1 paper, 2022). "However, further research is needed to confirm whether the escitalopram-induced expression of CREB3L4 gene might be implicated in mechanism of the UPR pathway activation in depression." (PMID 35456680, 2022).
dilated cardiomyopathy (1 paper, 2018). Cardiomyopathy which is characterized by dilation and contractile dysfunction of the left and right ventricles. "KEGG pathway analysis on cardiac loop genes reveals enrichments for terms, such as dilated cardiomyopathy, vasopressin-regulated water reabsorption, and hypertrophic cardiomyopathy (the genes within these terms include: Adcy6, Aqp3, Creb3l4, Des, Itgb5, Itga9, Myl2, Myl3, and Stx4a)." (PMID 30697540, 2018).
Impaired glucose tolerance (1 paper, 2020). An abnormal resistance to glucose, i.e., a reduction in the ability to maintain glucose levels in the blood stream within normal limits following oral or intravenous administration of glucose. "CREB3L4, which regulates adipogenesis, has for instance been recently shown to have a critical role in metabolic phenotypes (weight gain, impaired glucose tolerance and decreased insulin sensitivity)." (PMID 32134384, 2020).
prostate tumour (1 paper, 2024). "CREB3L4 has been shown to directly interact with AR in LNCaP cells to increase cellular proliferation and is abundantly expressed in prostate tumour tissue." (PMID 38878676, 2024).
triple-negative breast carcinoma (1 paper, 2024). An invasive breast carcinoma which is negative for expression of estrogen receptor (ER), progesterone receptor (PR), and human epidermal growth factor receptor 2 (HER2). "We found that CREB3L4 is highly upregulated in a specific subtype of triple-negative breast cancer, the intraluminal androgen receptor (LAR) subtype, and can be used as a potential therapeutic target." (PMID 39254691, 2024).
cancer (12 papers, 2015 to 2026). A tumor composed of atypical neoplastic, often pleomorphic cells that invade other tissues. "CREB3L4 has been shown to be associated with the development of cancers." (PMID 28056099, 2017). "This region contains many oncogenes such as CREB3L4 and MDM2 and increase in their copy number has been linked with worse survival for many human cancers." (PMID 28969054, 2017). "CREB3L4 is an endoplasmic reticulum membrane-bound transcription factor that has been shown to regulate the expression of Bcl-2 associated athanogene 3 (BAG3), a co-chaperone protein involved in autophagy and survival signaling in various cancers." (PMID 42098970, 2026). "Finally, RHEB knockdown reversed the promoting effects of CREB3L4 on the proliferation of cancer cells." (PMID 38303702, 2024). "How does CREB3L4 regulate androgen-dependent cancer cell proliferation?" (PMID 28338058, 2017). "For the limitation of the study, we did not utilize the inhibitor of mTORC1 signaling pathway in the animal models, with which to investigate whether CREB3L4 could facilitate malignancy through activating mTORC1 pathway, or reduce the sensitivity of cancer cells to sorafenib." (PMID 38303702, 2024). "In the future, more studies are required to identify the efficiency of CREB3L4 as a new therapeutic target of HCC, together with the appropriate application of anti-cancer therapy for the patients with high CREB3L4 expression." (PMID 38303702, 2024). "KEGG pathway enrichment analysis showed that CCNE2, MYC, CREB3L4, and NKD2 are involved in many tumor-related pathways, suggesting that these genes may play an essential role in cancer development." (PMID 28056099, 2017).
tumor (6 papers, 2016 to 2025). "Xenografted tumor model was established to define the regulatory effects of CREB3L4 in the tumorigenesis." (PMID 38303702, 2024). "In addition, exogenous CREB3L4 inhibition in vivo significantly inhibited the proliferation of HCC cells, indicating that CREB3L4 could function as a tumor promoter in HCC." (PMID 38303702, 2024). "To further verify the roles of CREB3L4 in progression and chemosensitivity of HCC under in vivo conditions, we constructed HCC xenografted tumor models based on LV-shCREB3L4 and LV-shNC HCC cell lines." (PMID 38303702, 2024).
CREB3L4 also shares sentences with these, for which no sentence is quoted: metabolic disorders (3 papers); cocaine addiction (2); colorectal cancer (2); infection (2); metabolic syndrome (2); Alzheimer ́s disease (1); cardiac hypertrophy (1); cardiac ischemia (1); cervical cancer (1); Charcot-Marie-Tooth disease (1); chronic pancreatitis (1); colon carcinoma (1); Diarrhea (1); Fundus dystrophy (1); Glucose intolerance (1); Hepatic steatosis (1); hypertriglyceridemia (1); hypertrophic cardiomyopathy (1); Immunodeficiency (1); kidney cancer (1); lung carcinoma (1); nemaline myopathy (1); nephronophthisis (1); nephrotic syndrome (1); non-syndromic intellectual disability (1); pancreatic cancer (1); pancreatic disease (1); Parkinson disease (1); prostatic diseases (1); prostatic intraepithelial neoplasia (1).
A further 4 diseases each share a sentence with CREB3L4 in 1 paper.